CTLA4 (cytotoxic T-lymphocyte associated protein 4)
Diseases named in the same sentence as CTLA4 in open-access papers (continued):
Sharing a sentence is not in itself a finding about the gene and the disease.
tumor (continued). "The result showed that although treatment with the MUC1 vaccine or CTLA-4 siRNA-containing NLE could increase the number of CD8+ T cells infiltrating the tumor, the combination therapy was most effective in promoting the infiltration of CD8+ T cells compared to the individual treatments." (PMID 40943370, 2025). "Immune checkpoint blockade (ICB) treatments, such as anti-PD1/PDL1 and anti-CTLA4 therapies, which are correlated with immune regulation, showed value in reinvigorating “exhausted” T cells and controlled tumor growth, which have succeeded in some clinical tumor treatments." (PMID 39776803, 2025). "Furthermore, CTLA-4 has been found to be expressed on various tumor cells." (PMID 40006624, 2025). "Additionally, higher levels of Treg cells were found in the primary tumor tissue, expressing elevated levels of costimulatory genes associated with immune checkpoints (CD27, ICOS, TNFRSF4, and TNFRSF18) and exhaustion markers (CTLA4 and TIGIT)." (PMID 40303346, 2025). "Furthermore, METTL1 can directly influence tumor responsiveness to immunotherapy by regulating key immune checkpoints (e.g., PD-L1, CTLA-4), immune regulatory molecules (modulating interferon signaling), and proinflammatory immune cell activity, indicating its potential as a therapeutic target." (PMID 41562049, 2025). "Expression of PD‐L1, PD‐1 and CTLA‐4 mRNA was observed in pigmented and/or non‐pigmented atypical cells with vesicular nuclei and prominent nucleoli interpreted as tumour cells, as well as in non‐tumour cells, mostly characterised by scant cytoplasm, interpreted as small lymphocytes." (PMID 39789732, 2025). "Additionally, correlations between CD68 expression and six TIICs (B cells, CD4+ T cells, CD8+ T cells, macrophages, NK cells, and cancer-associated fibroblasts) or four common TICs (PDCD1, CTLA4, IDO1, and CD40) were assessed using the Tumor Immune Estimation Resource (TIMER)." (PMID 40918116, 2025). "Indeed, the broadening of the peripheral BCR repertoire by anti–CTLA-4 may not only include self-reactive clones but potentially also B cells that may express tumor self- or neoantigen-reactive BCRs." (PMID 41026527, 2025). "Commonly used ICI include blockade of cytotoxic T-lymphocyte associated protein 4 (CTLA-4) and programmed cell death protein 1 (PD-1) pathways, alone or in combination to rejuvenate exhausted immune cells, including cytotoxic (CD8+) T cells to promote tumor cell killing." (PMID 40313772, 2025). "We reasoned that the CTLA4‐high subtype could be identified by immunocyte infiltrate populations and utilised the computational framework CIBERSORTx to discern the composition of tumour‐infiltrating immune cells from bulk RNA‐seq data." (PMID 39828982, 2025). "CTLA-4 inhibits T-cell proliferation and enhances Treg activity, while PD-1, expressed on multiple immune cells, suppresses antigen-specific T-cell responses upon binding PD-L1, which is upregulated in tumor and stromal cells and correlates with poor prognosis." (PMID 41012682, 2025). "The combination therapies involving these novel ICs – whether in conjunction with PD-1/PD-L1 and CTLA-4, or in collaboration with nanomaterials, oncolytic viruses (OVs) and tumour vaccines – have ignited a wave of research enthusiasm, offering new hope for immunotherapy in HNSCC." (PMID 40994140, 2025). "Recent studies have revealed marked variability in PD-1 or CTLA-4 expression among individuals and across different tumour sites in patients with HNSCC, a disparity that may contribute to suboptimal responses to PD-1/PD-L1 and CTLA-4 therapies in a subset of these patients." (PMID 40994140, 2025). "Moreover, as previously demonstrated by us, SC models show a rapid accumulation of Treg cells during tumor progression; Moreover SC models might be more reasonable to apply CTLA4 blockade in the late stage." (PMID 40899264, 2025).
tumor (continued). "Moreover, when CT26 and MC38 tumor-bearing mice were treated with 225Ac-labeled anti-CCR8 antibody followed by anti-CTLA4 immune-checkpoint-inhibiting immunotherapy, the synergistic slowing down of tumor progression and increase in animal survival were observed." (PMID 41302499, 2025). "Additionally, elevated expression of immune checkpoint genes (e.g., PDCD1 and CTLA-4) in the high MDK-NCL group suggests that this pathway might promote immune evasion by enhancing the tumor’s dependence on checkpoint mechanisms." (PMID 40396179, 2025). "On the basis of our studies, we would predict that blocking CTLA-4 may promote intracellular CD80 and PD-L1 signals that may increase DC migration, and it is possible that in the clinic, this is a mechanism that affects the efficacy of CTLA-4 blockade in a tumor setting." (PMID 39879305, 2025). "Similarly, CTLA-4 expression in Treg cells is also elevated following treatment with IL-2cx20 which may inhibit priming of tumor-specific T cells." (PMID 40789741, 2025). "Serum ObR was also positively correlated with serum cytotoxic T lymphocyte-associated antigen 4 (CTLA-4), tumor necrosis factor α (TNF-α), programmed death protein-1 (PD-1), and programmed death ligand-1 (PD-L1), while showing an inverse correlation with ObR expression in tumor tissues." (PMID 41150099, 2025). "For example, blocking the negative IC molecules cytotoxic T-lymphocyte-associated protein 4 (CTLA-4) or the programmed cell death protein 1 and its ligand 1 (PD-1/PDL-1) has been shown to reactivate cytotoxic immune cells and support efficient tumour rejection." (PMID 40317320, 2025). "We recently provided evidence that activin was associated with increased expression of CTLA-4, CD25, and PI3K activation in the tumor microenvironment (TME) suggesting that this molecule may be promoting expression of these checkpoint markers through the PI3K pathway." (PMID 40075112, 2025). "Such upregulation may indicate heightened immune cell activity within the tumor microenvironment and imply that these patients potentially exhibit a more favorable response to immune checkpoint inhibitors, such as anti-PD-1/PD-L1 and anti-CTLA-4 therapies." (PMID 41009979, 2025). "Over the past decade, ICIs targeting PD-1/PD-L1, CTLA-4, and other molecules that regulate the immune response against cancer have transformed the treatment of a wide variety of cancer types, enhancing survival, and in some cases even leading to complete tumor regressions." (PMID 40258833, 2025). "Antitumor activities of cytotoxic T and NK cells could be partially normalized by administration of immune checkpoint inhibitors (ICIs) such as antibodies against especially PD-1 or CTLA-4, which have produced unprecedent progression-free and even tumor-free survival in many cancer patients." (PMID 40170468, 2025). "Ipilimumab is a monoclonal antibody against cytotoxic T lymphocyte antigen-4 (CTLA-4), which is known to inhibit binding of CD80 and CD86 molecules on antigen-presenting cells, thereby causing proliferation and activation of T cells and promoting presentation of tumor antigen." (PMID 38187173, 2024). "They found that many immune checkpoint molecules, such as CTLA-4, PD-L1 and PD-L2, as well as TGFβ levels, were increased in response to radiation, thus turning an immunologically “cold” tumor into a “hot” tumor, which may translate into better response to immunotherapy." (PMID 39635522, 2024). "Several checkpoint and inhibitory receptors, such as PD-1 (gene name: PDCD1), CTLA4, TIM-3 (HAVCR2), LAG3, CD39 (ENTPD1), CD160, KLRG1, CD96, BTLA, 2B4, and TIGIT, have been implicated in the reduction of immune activity and response in the tumor micro-environment." (PMID 39513882, 2024).
tumor (continued). "One mechanism, by which the tumor cells escape the host’s immune response is the hijacking of immune-checkpoints, like programmed cell death ligand 1 (PD-L1), CD80, CD86 and their respective receptors, programmed death receptor 1 (PD-1) and cytotoxic T-cells associated protein 4 (CTLA-4)." (PMID 38962703, 2024). "These pre-clinical studies demonstrate that PET radiopharmaceuticals can be utilized to detect CTLA-4 expressing immune and tumor cells in vivo; however, further work is needed to determine if this radiopharmaceutical may be an effective agent to monitor response to immunotherapy clinically." (PMID 39104861, 2024). "For example, RORC agonists combined with the checkpoint inhibitor anti-CTLA-4 could enhance Th17 cell differentiation, migration, and infiltration, inhibit Treg cell production, increase the function of anti-tumor effector T cells, and inhibit the growth of MC38 COAD cells." (PMID 39252305, 2024). "Specifically, we reasoned that this strategy could reverse the high lactate-to-glucose ratio within tumors and destabilize tumor metabolism and Tregs, leading to enhanced therapeutic activity when combined with CTLA-4 blockade, based on our prior findings in genetically modified tumor models." (PMID 39225102, 2024). "While the loss of MHC and decrease of NK activity are fundamental for CTVT growth, further studies comparing different phases of the tumour’s growth, CTLA-4 expression in the tumour and local immune cells, and gene expression of CTLA-4 may provide more reliable evidence of CTVT immune escape." (PMID 38893123, 2024). "Therefore, utilizing pentoxifylline instead of anti-CTLA4 may hold the potential to downregulate irAEs and enhance the effectiveness of tumor immune responses." (PMID 39456702, 2024). "A tumour cell that expresses CD80/CD86 may interact with CTLA-4 and inactivate the immune cell." (PMID 39336171, 2024). "Therefore, blocking CTLA-4 can help control immune escape and promote the anti-tumor activity." (PMID 39275127, 2024). "Interestingly, anti-CTLA-4 treatment outperforms anti-PD-1 blockade in subcutaneous tumours." (PMID 39322643, 2024). "Although the inhibitory signal of CTLA4 negatively regulates T cell initiation and may induce immune rejection within the tumor nest, it subsequently induces PD-1-mediated T cell activation and proliferation, resulting in a killing effect on tumor cells." (PMID 38693304, 2024). "Pathological response to anti-PD-1, with and without anti-CTLA-4, has been shown to correlate with high interferon-γ expression and high tumor mutation burden, suggesting biomarker-driven treatment investigation may be appropriate." (PMID 38907159, 2024). "However, studies also revealed that anti-CTLA4 Ab could enhance the anti-tumor activity depending on the activation of Ab-dependent cellular phagocytosis (ADCP)." (PMID 38398223, 2024). "Furthermore, in NK cells, the generation capacity of IFNγ and perforin were dramatically increased on day 7 after treatment, with downregulated levels of CTLA-4 and Tim-3 compared to those in the tumor-bearing controls, suggesting the activation and improved cytotoxicity after cryo-thermal therapy." (PMID 38827732, 2024). "Furthermore, the combination of the anti-CTLA-4 treatment with vaccination induced complete tumor regression in 3/5 mice, and PD-L1 blockade combined with the vaccination promoted tumor regression in 2/5 mice, compared to only 1/5 mice achieving tumor regression with CCL11-E6E7 immunization alone." (PMID 38459592, 2024). "In addition, T cells display markedly elevated CTLA4 when contacted with tumor cells." (PMID 39575257, 2024). "Tumors that had initial high uptake of the CD3 radiopharmaceutical later had reduced tumor volume, with the authors concluding that higher initial radiopharmaceutical uptake was indicative of more T cell infiltration and heralded potential anti-CTLA-4 mediated ICI response." (PMID 39104861, 2024).
tumor (continued). "However, the immune escape mediated by antigen modulation, up‐regulated expression of inhibitory factors like CTLA‐4 and toll‐like receptors, and the generation of immunosuppressive environments of tumor cells has greatly limited the immunogenicity of tumor cells." (PMID 39463159, 2024). "Therefore, KCNK1 might reduce the potential for tumour immune escape and enhance immune response (anti-CTLA-4 and anti-PD-1 combination therapy) by modulating elevated potassium ions." (PMID 38689322, 2024). "However, the expression of suppressive molecules (PD-1 and CTLA-4) on the surface of CD8+ T cells increases in response to sustained stimulation by tumor-specific antigens, and their function decreases and eventually reaches the exhausted state, as demonstrated in multiple cancer models." (PMID 38291496, 2024). "Ipilimumab targets cytotoxic T lymphocyte antigen 4 (CTLA-4) on T cells, while Nivolumab and Pembrolizumab target programmed cell death protein 1 (PD-1) on T cells, and Atezolizumab targets programmed cell death ligand 1 (PD-L1) on tumour cells and tumour-infiltrating immune cells." (PMID 39000359, 2024). "Similarly, expression of CTLA-4 on the surface of T cells and binding to B7 molecules on DCs delivers an inhibitory signal that reduces T cell proliferation and activation and suppresses immune responses against tumor cells." (PMID 39273502, 2024). "Additionally, blocking IFN-γ in mice who received anti-CTLA-4 therapy also suppressed the induction of IDO in the tumor microenvironment, suggesting that the effector mechanism of immune checkpoint blockade may be mediated by IFN-γ." (PMID 38038862, 2024). "Therefore, we reasoned that knockout of CTLA4 in combination of CUL5 KO may further release the cytotoxic power of anti-tumor CD8+ T cells." (PMID 38242867, 2024). "Therefore, combining PD-1/PD-L1 inhibitors with other treatments like radiotherapy, chemotherapy, CTLA-4 inhibitors, or tumor vaccines may offer improved therapeutic outcomes." (PMID 39290699, 2024). "Moreover, CTLA-4 indirectly modulates immunosuppression in the tumor microenvironment (TME) by limiting CD4 + T cells' clonal expansion, which is essential for targeting malignant tumor cells through direct killing or enhancing cytotoxic T-cells and B-cells immune response." (PMID 38956700, 2024). "Specifically, the immune checkpoints mediated by cytotoxic T-lymphocyte associated antigen-4 (CTLA-4), programmed cell death-1 (PD1), and programmed cell death ligand 1 (PD-L1) inhibit T-cell activation through their interaction with antigen-presenting cells or tumor cells." (PMID 39590149, 2024). "Therefore, the application of monoclonal antibody to block CTLA-4 can relieve its inhibitory effects on T cells, reactivate T cell proliferation and differentiation into cytotoxic T lymphocytes (CTLs), thereby exerting anti-tumor immune effects." (PMID 38177102, 2024). "Additionally, when ICIs inhibit CTLA-4/PD-1/PD-L1, the “immune brake” of the body is released, which not only strongly activates the immune ability of T cells to tumour cells, but also leads to the decrease in the tolerance of the kidney to endogenous antigens, thus triggering AKI." (PMID 39011500, 2024). "This suggests that tumor-specific T cells, limited by tumor cell expression of PD-L1 may exist in greater numbers in B16-F10 tumors, explaining why PD-1 blockade was more successful in B16-F10 and CTLA-4 blockade in CT26LacZ models." (PMID 38328418, 2024). "Importantly, survival of mice could be further and significantly improved by combining anti-CTLA4 therapy with additional RT of the primary tumor in ABx and H2O mice." (PMID 38500667, 2024). "During the activation stage of T cells, the concurrent administration of CTLA-4 and PD-L1 inhibitors synergistically enhances the continuous and accelerated activation of effector T cells, facilitating their extensive proliferation and migration towards the tumor microenvironment." (PMID 39038010, 2024).
tumor (continued). "Our mechanistic study revealed that TBC1D1-mediated inhibition of CTL function could be attributed to the upregulation of various immune checkpoint molecules, including ARG1, CD68, PDCD1, CD274, TGFB1, and CTLA4, collectively impeding the anti-tumor immune response." (PMID 38529286, 2024). "For instance, one effective approach could involve combining a mAb that amplifies the activity of preexisting tumor-reactive T cells, such as a 4-1BB agonist or a PD-1/PD-L1-blocking antibody, with another mAb that diversifies the pool of tumor-reactive T cells, such as a CTLA-4 blocking-antibody." (PMID 38172595, 2024). "Several murine studies have suggested CTLA-4 blockade may impair the suppressive activity of Tregs and deplete Tregs within the tumor microenvironment (TME) via antibody-dependent cell-mediated cytotoxicity (ADCC) resulting in reduced tumor immunosuppression and expansion of effector T cells." (PMID 38459592, 2024). "In addition, anti-CTLA-4 treatment may reduce the risk of resistance to anti-PD1 in some patients with low PD-L1 expression and show a synergistic anti-tumor effect." (PMID 38928307, 2024). "Additionally, it demonstrated equivalent antitumor efficacy to that of the commercially available anti-CTLA-4 MAB (Ipilimumab Yervoy®) in a humanized murine tumor model, implying that the plant-derived anti-CTLA-4 MAB has similar therapeutic potential to that of the clinically efficient Ipilimumab." (PMID 39851281, 2024). "The review focuses on indicators, including PD-L1, CTLA-4, and tumor mutational burden (TMB) in predicting immunotherapy responses, highlighting recent developments in our understanding of the intricate interactions between tumor genetics and the immune milieu." (PMID 39452555, 2024). "However, using both PD-1–blocking and cytotoxic T lymphocyte–associated protein 4–blocking (CTLA-4–blocking) antibodies in combination with TH-302 and αVEGFR-2 failed to improve tumor responses." (PMID 37988164, 2024). "Therefore, drugs targeting CTLA-4 hold significant promise for tumor immunotherapy." (PMID 39080807, 2024). "Based on immunophenotyping tumours, we speculate that this differential effect may, in part, be attributed to the capacity of anti-CTLA-4 blocking the CTLA-4 immunosuppressive properties such as attenuation of CD28 signalling through binding of CD80/8635,52,53." (PMID 39322643, 2024). "In addition to the changes in the tumor immune microenvironment, an increased expression of PD-L1 in tumor cells, promoter methylation of CTLA4, LAG3, and PD-L1, and an abnormal expression of microRNAs can affect the efficacy of ICIs in NSCLC patients with COPD." (PMID 38291354, 2024). "While we find that anti-CTLA-4 or anti-PD-1 can synergize with neo VAX in different tumor models when we give the first NeoAg vaccine and ICT mAb at the same time, the timing of treatment may impact the response in certain situations, as observed in other models and vaccine settings." (PMID 38187708, 2024). "CircWDR25 (hsa_circ_004310) and circQSOX1 (hsa_circ_0015497) could also promote the increased expression of CTLA-4 and PD-L1 through the sponge mechanism in hepatocellular carcinoma and colorectal cancer, respectively, thus driving tumor immune escape and promoting cancer progression." (PMID 38177102, 2024). "Notably, cytotoxic T-lymphocyte-associated protein 4 (CTLA4) and PD-1 (PDCD1) genes serve as exemplars of immune checkpoint genes, and the application of antibody therapy to inhibit the CTLA4 or PD-1 checkpoints has been shown to unleash T-cells for tumor eradication." (PMID 38164277, 2024). "However, this local RT + IL-12 therapy at the large right flank tumor site in combination with systemic srIL-2 and anti- CTLA-4 induced a systemic antitumor effect mediating an adaptive, T cell dependent, response at the distant left tumor site that did not get direct RT + IL-12." (PMID 39076988, 2024).